REN (renin)
Diseases named in the same sentence as REN in open-access papers (continued):
Sharing a sentence is not in itself a finding about the gene and the disease.
COVID-19 (continued). "COVID-19 invades human cells through binding with angiotensin-converting enzyme 2, and some research shows that the renin-angiotensin-aldosterone system’s imbalanced activity in obese individuals contributes to this pathogenesis." (PMID 34777870, 2021). "In this study, we aim to analyze elderly patients hospitalized with COVID-19 and evaluate the relationship between renin–angiotensin–aldosterone system (RAAS) inhibitors and mortality." (PMID 34300311, 2021). "The SARS-CoV-2 infection resulted in ACE2 dysfunction and worsened COVID-19 by dysregulating the renin-angiotensin-aldosterone system, leading to multiorgan failure." (PMID 34025650, 2021). "Based on this purported ACE2 double function, it has been put forward that the benefit from ACE2 upregulation with renin–angiotensin–aldosterone system inhibitors (RAASi) counterbalances COVID-19 risks due to counter-regulatory RAS axis amplification." (PMID 34501332, 2021). "Our result that ACE2 association has a minimal impact on rates of AKI in hospitalized patients provides a rationale for trials of renin-angiotensin system inhibitors for the therapeutic management of COVID-19." (PMID 34733538, 2021). "Concern had been raised about the potential effect of renin–angiotensin–aldosterone system (RAAS) blockades on renal outcomes in COVID-19 patients." (PMID 34193877, 2021). "Reports on the effects of renin–angiotensin–aldosterone system (RAAS) inhibitors on the clinical outcomes of coronavirus disease-19 (COVID-19) have been conflicting." (PMID 34090358, 2021). "Given the impact of the pandemic, we summarized the available updates on the multidisciplinary approaches for the therapeutic strategies for COVID-19 related with the renin-angiotensin-aldosterone system (RAAS) and kallikrein-kinin system (KKS) components." (PMID 34925477, 2021). "In skin microbiota, four pathways on KEGG level 3, including sphingolipid signaling pathway, coronavirus disease (COVID-19), steroid degradation, and renin secretion were significantly different between the two groups." (PMID 34050205, 2021). "The effect of renin–angiotensin–aldosterone system (RAAS) inhibitors on the clinical outcomes of coronavirus disease-19 (COVID-19) is of great interest." (PMID 34090358, 2021). "High expression of ACE2 in COVID-19 patients lead to an imbalance of renin-angiotensin-aldosterone system (RAAS), which participates in the regulation of electrolytes and blood flow." (PMID 34539642, 2021). "Modulation of the renin-angiotensin system has been mentioned by others to explain the severity of COVID-19." (PMID 32793244, 2020). "COVID-19+ patients were more likely to be black, have comorbid conditions, and were less likely to be on renin angiotensin blockade at time of testing." (PMID 32997657, 2020). "ACE2, a gene involved in the renin-angiotensin system, has been shown to be a therapeutic target in COVID-19, as SARS-CoV-2 uses ACE2 as a receptor to enter host cells." (PMID 32754224, 2020). "Comorbid conditions associated with COVID-19, such as diabetes and hypertension, are also modulated by ACE2 and the renin–angiotensin system (comorbidity section)." (PMID 33396584, 2020). "It has been seen here, for example, that between 1 in 10 and 2 in 5 of those hospitalised with COVID-19 were taking medicines acting on the renin–angiotensin system in the month before their hospital admission." (PMID 33024121, 2020). "SARS-CoV-2-ACE2 interaction has generated great interest in the development of renin-angiotensin system-based therapeutic strategies for COVID-19." (PMID 33256258, 2020). "Persistent low-grade inflammation, dysregulation of the renin–angiotensin system, insulin resistance, and increased tissue stiffness in these patients can lead to an overexpression of pro-inflammatory cytokines in response to COVID-19." (PMID 40283075, 2025).
COVID-19 (continued). "Patients with COVID-19 often present predominantly with hypokalemia, which may be due to increased urinary potassium excretion due to overactivation of the renin–angiotensin–aldosterone system." (PMID 40423181, 2025). "Dysregulation of the renin–angiotensin system (RAS) is linked to COVID-19, but also to non-COVID-19 ARDS." (PMID 39821855, 2025). "Acute COVID-19 disease may also stimulate the renin–angiotensin–aldosterone system (RAAS), and persistent activation of RAAS and/or endothelial injury has been reported among patients with COVID-19; both are associated with blood pressure elevation." (PMID 40503239, 2025). "Acute cardiac injury in COVID-19 is thought to involve a complex interplay of factors, including direct viral cytopathic effects, immune response dysregulation and dysfunction of the renin–angiotensin–aldosterone system (RAAS)." (PMID 39738791, 2025). "Our results suggested that dysregulation of the renin–angiotensin system due to the ACE2 downregulation activity of the S protein of SARS-CoV-2 may play a key role in the pathogenesis of COVID-19." (PMID 38279353, 2024). "The pathophysiology of AKI related to COVID-19 is complex, and systemic inflammation and immune response, activation of the coagulation pathway, renin—angiotensin system, endothelial injury, and other factors are involved in the renal failure process occurring in COVID-19 patients." (PMID 38668323, 2024). "Findings from clinical trials suggest that both statins and renin–angiotensin–aldosterone system inhibitors (RAASI) might have the potential to reduce unfavorable outcomes in patients with COVID-19." (PMID 39518552, 2024). "Vitamin D also influences the renin-angiotensin system by downregulating the expression of renin, which may have implications in COVID-19 pathophysiology given the virus's interaction with the ACE2 receptor." (PMID 39564063, 2024). "Furthermore, increased ACE-2 expression and dysregulated activation of the renin–angiotensin–aldosterone system were found in obese individuals, indicating a role in the pathophysiology of COVID-19." (PMID 39311212, 2024). "Angiotensin-converting enzyme 2 (ACE2), a key regulator in vasoregulation and the renin–angiotensin system, is hypothesized to be downregulated in patients with COVID-19, leading to a cascade of cardiovascular complications." (PMID 39051242, 2024). "In COVID-19 patients, vitamin D supplementation may lessen cytokine storms by influencing the activity of the renin–angiotensin system and the production of ACE2." (PMID 36769240, 2023). "Smoking and air pollution may adversely modulate the Renin-angiotensin system (RAS) and increase the risk of COVID-19 development." (PMID 37142990, 2023). "In addition to insulin resistance, inflammatory responses, the renin–angiotensin system, and other factors such as clotting factors, hemoglobin, obesity, hypokalemia, and hypovitaminosis D were also affected by COVID-19 in diabetic patients." (PMID 36839456, 2023). "The renin–angiotensin system (RAS) blockers may enhance COVID-19 by boosting the expression of ACE2." (PMID 36839456, 2023). "Moreover, two COVID-19-related genes, Klk1 and Klk1b5, identified in the Renin-angiotensin system (RAS) in the network analysis, were upregulated by the CO diet in the duodenum." (PMID 37886485, 2023). "Additionally, vitamin D exhibits potential inhibitory effects on renin, an enzyme that induces the expression of angiotensin II (ang II), thereby potentially reducing the severity of COVID-19." (PMID 37299555, 2023). "The effect of resveratrol on the two opposite pathways in the renin–angiotensin system (RAS) may equally be useful in COVID-19 patients." (PMID 37299603, 2023). "Therefore, although a definitive conclusion is yet to be made, the current narrative is that the use of Renin–Angiotensin–Aldosterone inhibitors exerts potential clinical benefit in COVID-19 patients." (PMID 37479767, 2023).
COVID-19 (continued). "Therefore, dysregulation of the renin/angiotensin system is a potential unifying mechanism for our findings of increased Tie-2 and Flt-1 in post-COVID-19 patients." (PMID 36844209, 2023). "Alterations in the renin–angiotensin system (RAS), with consequent activation of the NLRP3 (NOD-like receptor 3) inflammasome, is the probable reason why hypertensive patients are more susceptible to severe forms of COVID-19." (PMID 37371071, 2023). "While the exact mechanism underlying vascular thickening during SARS-CoV-2 infection is not fully understood, the disruption of the renin-angiotensin system during COVID-19 could contribute to this anomaly." (PMID 35740365, 2022). "On the other hand, lower levels of ACE-2 may influence severity of COVID-19, possibly via the renin-angiotensin-aldosterone system." (PMID 35852992, 2022). "The COVID-19-induced lung injury may affect the cardiopulmonary hemodynamics and left atrial underfilling with subsequent activation of renin–angiotensin–aldosterone system and AVP/copeptin release." (PMID 35350852, 2022). "In individuals with hypertension, use of a renin–angiotensin system inhibitor was not linked to higher mortality or severity of COVID-19, according to a comprehensive review and meta-analysis." (PMID 36363511, 2022). "RNA-Seq data from cells in bronchoalveolar lavage fluid from COVID-19 patients have pointed out dysregulation of kallikrein-kinin and renin-angiotensin systems as a possible mechanism that triggers multi-organ damage away from the leading site of virus infection." (PMID 36601349, 2022). "For patients with COVID-19, severe systemic hyperinflammation, increased autoantibody reactivity, and over-activation of the renin-angiotensin system were all identified, which may be related to the myocardial mid-wall fibrosis." (PMID 36386376, 2022). "In addition to acting as a receptor for severe acute respiratory syndrome coronavirus 2, the causative virus of COVID-19, angiotensin converting enzyme 2 (ACE2) contributes to tryptophan absorption and inhibition of the renin-angiotensin system." (PMID 35463998, 2022). "The protective effect of vitamin D by the renin-angiotensin system concerning COVID-19 remains unclear." (PMID 35172759, 2022). "Determining how various immune aberrancies, including those described here and others such as elevated IL-6 or an impaired renin-angiotensin system might contribute to the pathogenesis of severe COVID-19 will require the development of new animal models." (PMID 35040666, 2022). "In this regard, ACE2 plays an important role in inflammation and thrombotic response, and its down-regulation may aggravate COVID-19 via the renin-angiotensin system, including by promoting pathological changes in lung injury." (PMID 35053224, 2022). "The underlying mechanisms of COVID-19-associated AKI are likely multifactorial, including local and systemic inflammatory and immune responses, endothelial injury and hypercoagulability, and the renin-angiotensin system, direct viral infection." (PMID 35678258, 2022). "Moreover, vitamin D was found to play a moderating role in the renin–angiotensin–aldosterone system (RAAS) involved in the pathogenesis of COVID-19." (PMID 36558489, 2022). "We note that COVID-19-induced downregulation of ACE2 may be involved in modulating both the renin-angiotensin system and activation of AP-1/p38MAPK signaling." (PMID 35216673, 2022). "ACE2 plays an important role in inflammation and the thrombotic response, and its down-regulation may aggravate COVID-19 via the renin-angiotensin system, including by promoting pathological changes in lung injury." (PMID 35053224, 2022). "This gene encodes the angiotensin-converting enzyme in the renin-angiotensin-aldosterone system (RAAS), which is involved in the blood pressure regulation and electrolyte balance, and possibly also in the pathophysiology of COVID-19." (PMID 36430729, 2022).
COVID-19 (continued). "The American Heart Association, the American College of Cardiology, and the Heart Failure Society of America issued a joint statement that renin-angiotensin-aldosterone system antagonists, such as ACEi and ARBs, should be continued as prescribed for patients with COVID-19." (PMID 36304162, 2022). "Finally, Vitamin D deficiency is a risk factor for COVID-19 that is also related with low levels of ACE2 because Vitamin D inhibits the expression of Renin, which in turn produces Ang1-10, the substrate from which is cleaved Ang1-8, which downregulates ACE2." (PMID 34322518, 2021). "Additionally, high levels of inflammation in severe COVID-19 patients perturbs the renin-angiotensin system." (PMID 34677394, 2021). "Activation of the renin-angiotensin system (RAS) in a hypertensive patient may contribute to lung injury among COVID-19 patients by promoting an inflammatory response (cytokine storm)." (PMID 34249180, 2021). "Fittingly, plasma renin concentration was upregulated in SARS-CoV-2 ARDS patients in our study, compared to non-ARDS COVID-19 patients, underlining the pivotal role of RAS activation for the course of COVID-19." (PMID 34945736, 2021). "Moreover, the renin-angiotensin-aldosterone system (RAS) seems to be critically involved in the pathophysiology of COVID-19." (PMID 34945736, 2021). "Moreover, we recently postulated that androgens, via alterations in the intrarenal renin-angiotensin system, impair renal hemodynamics, predisposing patients to acute kidney injury during COVID-19 infection, which could explain the higher mortality observed in men with COVID-19." (PMID 33922918, 2021). "Renin–angiotensin system was identified as a center of COVID-19 pathophysiology." (PMID 34554559, 2021). "ACE2 plays a pivotal role in the inflammation, and its downregulation may aggravate COVID-19 via the renin-angiotensin system, including by promoting pathological changes in lung injury and involving inflammatory responses." (PMID 33029758, 2021). "Alternatively, it has also been proposed that Beta-adrenergic blockers decrease the renin level by their inhibitory action on the sympathetic system, which may produce beneficial effects in COVID-19 patients." (PMID 34093217, 2021). "There are contradictory hypotheses on the potential benefit–risk profiles of antihypertensive drugs that act on the renin–angiotensin system for the treatment of COVID-19 patients." (PMID 34440554, 2021). "COVID-19 xerostomia is pathogenically related to viral cellular entry-relevant protein expression, renin-angiotensin system disturbance, salivary gland inflammation, zinc deficiency, cranial neuropathy, intercurrent taste dysfunction, comorbidities and medications." (PMID 34821594, 2021). "Many older adults are currently treated with renin–angiotensin–aldosterone system (RAAS) inhibitors and there is concern that these medications might increase the risk of mortality by COVID-19." (PMID 34300311, 2021). "Coronavirus disease 2019 (COVID-19) is a rapid-spread infectious disease caused by the SARS-CoV-2 virus, which can culminate in the renin-angiotensin-aldosterone (RAAS) and kallikrein-kinin (KKS) systems imbalance, and in serious consequences for infected patients." (PMID 34925477, 2021). "Based on experimental evidence, blocking the renin-angiotensin-aldosterone system might even exert a potentially protective influence in the setting of COVID-19." (PMID 34220496, 2021). "Therefore, they advocated for discontinuation/cautious use of such drugs in patients with COVID-19 that down-regulate the renin-angiotensin-aldosterone system (RAAS) system." (PMID 33494713, 2021). "In addition, we report an observational study of renin–angiotensin–aldosterone system inhibitors and severe COVID-19 outcomes using data (n = 50,821) from NYPH-WCMC and New York-Presbyterian Hospital-Columbia University Irving Medical Center (NYPH-CUIMC)." (PMID 33712587, 2021).
COVID-19 (continued). "Consequently, lifestyle changes, glycemic control, and regulation of the renin-angiotensin-aldosterone pathway have crucial implications for preventing and managing subjects with COVID-19." (PMID 34229605, 2021). "The renin–angiotensin system (RAS) may have an important role into the pathogenesis of the COVID-19." (PMID 33648544, 2021). "Apart from further exploring the possible benefit of chemical renin-angiotensin-aldosterone system inhibitors in COVID-19 patients, another promising approach might consist of the treatment of COVID-19 with human recombinant soluble ACE2." (PMID 32514935, 2020). "Recent clinical reports highlight an atypical presentation of acute respiratory distress syndrome (ARDS) in COVID-19 patients characterized by severe hypoxemia, an imbalance of the renin–angiotensin system, an increase in thrombogenic processes, and a cytokine release storm." (PMID 33138181, 2020). "Random clinical trials evaluating the role of medication that act on the renin-angiotensin-aldosterone pathway are needed before any conclusions can be reached regarding a potential relationship between these agents and the progression of COVID-19." (PMID 32587104, 2020). "In our study ACE, REN, INS, KNG1, and AGT showed the highest connectivity within the complete ACE2 network and association with enriched diseases that are known to be a risk factor for a severe course of COVID-19." (PMID 33233425, 2020). "We hypothesize that dysregulation of some of the key components of the renin-angiotensin system could be related to the lung injury and worsening observed in COVID-19." (PMID 32575076, 2020). "These obesogenic comorbidities affect the renin–angiotensin system resulting in metabolic imbalance and excess pro-inflammatory response; as a consequence, obese patients with COVID-19 may experience severe symptoms." (PMID 33396584, 2020). "Therefore, the impact of the modulation of ACE2 and the related renin-angiotensin-aldosterone system genes on COVID-19 has been an area of interest, and these genes were included in the current study." (PMID 32992731, 2020). "It has been hypothesized that two hits to the renin-angiotensin system drive COVID-19 progression in those with pre-existing inflammation." (PMID 33256258, 2020). "A central pathway in the pathophysiology of COVID-19 is the renin–angiotensin system (RAS)." (PMID 33138181, 2020). "Additionally, vitamin D influences the renin-angiotensin system and has anti-thrombotic effects, which are critical in the context of COVID-19, and may help resolve the harmful pro-inflammatory responses seen in severe cases." (PMID 40211163, 2025). "Orthostatic intolerance emerging post-COVID-19 has been attributed to possible dysfunction in inflammatory and autoimmunity pathways, changes in signaling along the neuro-cardiac axis or hypovolemia mediated by renin-angiotensin-aldosterone system (RAAS) disbalance." (PMID 40001603, 2025). "As the RAS is activated in VILI and in ARDS, this may have influenced renin and aldosterone levels in patients with COVID-19 in these studies and, apart from methodological differences, may explain the differing results that aldosterone levels were lower or higher in patients with severe COVID-19." (PMID 39821855, 2025). "The low expression of angiotensin-converting enzyme 2 (by monocytes/macrophages) in patients with COVID-19 may also contribute to the development of pathological reactions due to the pro-inflammatory properties of angiotensin II and dysfunction of the renin–angiotensin system." (PMID 38667325, 2024). "The renin–angiotensin system is crucial for blood pressure regulation and fluid balance, and its involvement may explain some of the cardiovascular manifestations seen in COVID-19." (PMID 39766256, 2024). "Additionally, the Renin–Angiotensin–Aldosterone System (RAAS) and Kinin–Kallikrein System have been implicated in the pathophysiology of COVID-19 and could contribute to the observed cardiovascular complications." (PMID 39685724, 2024).